JAK2 (Janus kinase 2)
Diseases named in the same sentence as JAK2 in open-access papers (continued):
Sharing a sentence is not in itself a finding about the gene and the disease.
acute myeloid leukemia (continued). "Adults with JAK2-V617F+ MPNs can evolve into acute myeloid leukemia (AML)." (PMID 24744787, 2014). "JAK2 was identified as a potential target based on the intersection of N2-predicted targets with known targets of acute myeloid leukemia (AML)." (PMID 39791711, 2024). "The presence of the JAK2-V617F mutant kinase renders acute myeloid leukemia (AML) cells less sensitive to CARM1 inhibition, and we show that the dual targeting of JAK2 and CARM1 is more effective than monotherapy in AML cells expressing phospho-CARM1." (PMID 38649367, 2024). "In addition, JAK2/FLT3 dual inhibitors could provide better therapeutic option for acute myeloid leukemia." (PMID 35631587, 2022). "Analysis of patients with acute myeloid leukemia (AML) sub types in other studies has shown that JAK2 V617F is present in a low proportion of patients." (PMID 31870101, 2019). "TG101209 is a potent and selective inhibitor of JAK2 (IC50 = 6 nM) that induces cell cycle arrest and apoptosis in Ba/F3 cells expressing the JAK2V617F mutation (IC50 = 170 nM) and in JAK2V617F-expressing acute myeloid leukemia cells through the inhibition of pJAK2V617F and pSTAT5." (PMID 22384256, 2012). "In cytogenetically normal acute myeloid leukemia, ME1 activates the interleukin (IL)-6/Janus kinase 2 (JAK2)/signal transducer and activator of transcription 3 (STAT3) pathway, which correlates with poor prognosis." (PMID 39996805, 2025). "TG-101,209 was a small molecule JAK2-selective kinase inhibitor, which had been proven to induce cell cycle arrest and apoptosis in the human JAK2V617F-expressing acute myeloid leukemia cell line." (PMID 39160604, 2024). "Similar paradoxical phosphorylation has been previously reported after incubation with JAK2 inhibitor Gö6976 and SB1518 in primary acute myeloid leukemia cells HEL92.1.7, and JAK inhibitor AZD 1480 in HL cells." (PMID 29515770, 2018). "Also, non-canonical, weakly activating germline JAK2 variants may predispose progenitor cells to acquire JAK2-V617F and accelerate MPN progression to acute myeloid leukemia (AML)." (PMID 40841769, 2025). "Here, we examine the signaling mechanisms from JAK2-V617F and responses to ruxolitinib in JAK2-V617F-positive leukemic cell lines, including PVTL-2, newly established from a patient with post-MPN secondary acute myeloid leukemia, and the widely used model cell line HEL." (PMID 29928488, 2018). "The JAK2-V617F mutation is also found, though much less frequently, in various other hematological malignancies, including acute myeloid leukemia (AML) and myelodysplastic syndrome (MDS), underscoring the importance of Jak2 in regulation of hematopoiesis." (PMID 24404189, 2014). "In acute myeloid leukemia (AML) cells, JOSD1 interacts with JAK2-V617F and promotes its expression." (PMID 36159990, 2022). "Moreover, the 46/1 haplotype of JAK2, possibly a marker of inappropriate myeloid cell response to cytokine stimulation, has been shown to pre-dispose carriers to IBD and myeloid malignancies, notably MPNs (with or without mutation of JAK2) and acute myeloid leukemia." (PMID 37284191, 2023).
pancreatic cancer (77 papers, 2010 to 2025). "JAK2 is closely associated with not only pancreatic cancer initiation and progression but also radiosensitivity." (PMID 33029256, 2020). "Furthermore, the decrease in pancreatic cancer cell proliferation caused by cucurbitacin I appeared to involve JAK2/STAT3 signalling pathway inhibition, and the use of JAK2/STAT3 activators effectively restored the inhibition." (PMID 35517401, 2022). "Selaginellin B from Selaginella tamariscina targets Janus kinase 2 (JAK2) to treat pancreatic cancer via autophagy modulation." (PMID 39403146, 2024). "Inhibiting JAK2/STAT3 signaling pathway activation was found to decrease pancreatic cancer growth and induce apoptosis both in vivo and in vitro." (PMID 38182570, 2024). "Activation of the Reg3A gene alters the JAK2/STAT3 pathway in pancreatic cancer cells, which can increase the expression of REG3A gene, forming a positive feedback mechanism to further promote the expression of REG3A in tumor cells." (PMID 37505298, 2024). "Activation of JAK2/STAT3 signaling in pancreatic cancer can lead to tumorigenesis, progression, cancer stem cell maintenance, and treatment resistance." (PMID 37642814, 2024). "Panaxadiol inhibits proliferation, and induced apoptosis of pancreatic cancer cells, and suppresses the growth of xenograft models by suppressing the JAK2/STAT3 pathway." (PMID 36814203, 2023). "MiR-216a significantly suppressed cell proliferation while induced programmed cell death in pancreatic tumor cells by inhibiting JAK2." (PMID 36740668, 2023). "This is the first evidence that CuI inhibits the proliferation of pancreatic cancer cells by suppressing JAK2 and STAT3 signal transduction." (PMID 35517401, 2022). "Relevant studies have shown that REG3A acts as a growth-promoting cell regulator and interacts with JAK2/STAT3 signaling to form a positive feedback loop to accelerate pancreatic cancer cell growth under IL-6-related inflammatory conditions." (PMID 36105933, 2022). "REG3A has been described as a proliferating factor following liver and skin injuries as well as a driver of pancreatic cancer cell growth through JAK2/STAT3 signaling pathways in response to interleukin-616,18." (PMID 34099862, 2021). "The results of bioinformatics analysis suggested that JAK2/STAT3 signaling was activated in pancreatic cancer tissues." (PMID 33029256, 2020). "In a pancreatic cancer mouse model, activation of JAK2/STAT3 signaling promotes stromal formation in tumors and can lead to gemcitabine resistance." (PMID 33029256, 2020). "Immunohistochemistry was used to evaluate JAK2 expression in human pancreatic cancer tissues, and its relationship with the clinical outcome was estimated." (PMID 33029256, 2020). "The aim of this study was to explore the prognostic value of JAK2 expression in patients with resectable pancreatic cancer." (PMID 33029256, 2020). "In a recent study, our team found that JAK2 inhibition increases the radiosensitivity of pancreatic cancer cells." (PMID 33029256, 2020). "For instance, miR-216a inhibited tumor cells growth by down-regulating the expression level of Janus kinase 2 (JAK2) in pancreatic cancer." (PMID 31798627, 2019). "• AG-490 treatment to block JAK2 inhibited Reg3A up-regulated expression of pJAK2 and pSTAT3 in pancreatic cancer SW1990, AsPC-1 cells and pancreatic epithelial HPDE6C7 cells." (PMID 31921694, 2019). "According to our previous study, EGFR, functioning as a REG3A receptor, mediated the REG3A signal-promoting human pancreatic cancer cell growth and JAK2/STAT3 activation." (PMID 28880262, 2017).
pancreatic cancer (continued). "Ruxolitinib (a specific JAK1/JAK2 inhibitor) was highlighted here based on its use in current phase 1, 2, and 3 clinical trials against pancreatic cancer (trials NCT01423604, NCT02117479, NCT02119663, and NCT01822756)." (PMID 27533247, 2016). "We found that in pancreatic cancer tissues, the expression of JAK2 correlated with the expression of mucin-16, which was associated with the preoperative serum CA125 levels of patients with pancreatic head cancer with LN16 involvement." (PMID 27081079, 2016). "Our pre-clinical work further builds upon these observations to characterize the activity of the BMS-911543 Jak2 inhibitor in a novel and highly aggressive murine model of spontaneously arising pancreatic cancer." (PMID 26575024, 2015). "Since JAK2, SOCS, JNK/SAPK, and Src signaling all converge and impinge on STAT3 signaling, our data suggests that loss of Cav-1 serves to reduce pancreatic cancer oncogenic proliferation, migration, invasion, and cell survival through a STAT3 mechanism." (PMID 26065715, 2015). "Finally, eckol protected against pancreatic cancer progression by downregulation of Janus kinase-2 (JAK2), STAT3, and NF-κB signaling pathways and cyclin D1 protein." (PMID 38894623, 2025). "Accordingly, simultaneous inhibition of KRAS, MEK, and JAK2 could be an innovative therapeutic strategy against KRAS‐mutant pancreatic cancer." (PMID 39400496, 2025). "Furthermore, CuI-induced suppression of pancreatic cancer cell growth appears to include JAK2/STAT3 signaling pathway suppression because JAK2/STAT3 activators successfully prevented the inhibition." (PMID 38397437, 2024). "MiR-216a reduced pancreatic tumor growth via JAK2 targeting." (PMID 36740668, 2023). "We speculate that this may be related to abnormal JAK2/STAT signalling pathway activation in pancreatic cancer." (PMID 35517401, 2022). "It has been reported that the JAK2/STAT1 pathway may be involved in the regulation of PD-L1 expression in pancreatic cancer cells, which is increased by gemcitabine or paclitaxel." (PMID 34359638, 2021). "As a key factor in the JAK/STAT pathway, JAK2 may be useful as a biomarker for predicting the prognosis of pancreatic cancer as well as a therapeutic target for patients with resectable PDAC." (PMID 33029256, 2020). "Elevated leptin may promote pancreatic tumor invasion and metastasis, activating the Janus kinase 2 (JAK2)/signal transducer and activator of transcription 3 (STAT3) axis." (PMID 33167521, 2020). "The findings of this study may improve our knowledge of the clinical significance and prognostic value of JAK2 expression in pancreatic cancer patients." (PMID 33029256, 2020). "JAK2 expression is correlated with pancreatic tumor cell metastasis and invasion." (PMID 33029256, 2020). "Forced expression of a 17 kDa MUC16-Cter fragment in pancreatic cancer cells mediated nuclear translocation of JAK2 which preferentially phosphorylated tyrosine 41 of histone H3 (H3Y41) in a STAT-independent manner and up regulated stemness specific genes LMO2 and NANOG." (PMID 29682172, 2018). "Taken together, our data suggest that MMP-13 may serve as a downstream effector of the leptin -JAK2/STAT3 cascade responsible for pancreatic cancer cell invasion." (PMID 25948792, 2015). "Given that activation of the JAK1 and JAK2 pathways has been demonstrated to inhibit tumour cell susceptibility to NK cells by upregulating PD-L1 expression 39, we further investigated the activation status of the JAK-STAT pathway in RBM10-knockdown pancreatic cancer cells." (PMID 40740233, 2025). "Additionally, another study indicated that stimulation of the 7-nAChR receptor increased pancreatic cancer metastasis through the activation of the Janus kinase 2 (JAK2)/STAT3 signaling pathway and the Ras/Raf/MAPK/ERK kinase (MEK)/extracellular signal-regulated kinases 1 and 2 (ERK1/2) pathways." (PMID 40940782, 2025).
pancreatic cancer (continued). "Our results confirmed that the expression of phosphorylated JAK1 (P-JAK1), phosphorylated JAK2 (P-JAK2), and phosphorylated STAT3 (P-STAT3) was upregulated in pancreatic cancer cells following RBM10 knockdown." (PMID 40740233, 2025). "This indirectly activates the Janus kinase 2 (JAK2)/signal transducer and activator of transcription 3 (STAT3) signaling pathway, allowing pancreatic cancer cells to become more treatment-resistant." (PMID 38911968, 2024). "The IL-6/JAK2/STAT3 signaling pathway is vividly involved in the pancreatic intraepithelial neoplasia (PanIN) and the development of pancreatic cancer." (PMID 39201692, 2024). "Panaxadiol has been found to inhibit the JAK2/STAT3 pathway, thus limiting the progression of pancreatic cancer." (PMID 37958803, 2023). "Indirubin derivative (IRD) E738, NS-018 and SKLB-850, dual JAK2/SRC inhibitors, have demonstrated inhibitory effects in pancreatic cancer, multiple myeloma and B-cell lymphoma." (PMID 37147297, 2023). "For example, cucurbitacin I reduces the levels of p-JAK2 and p-STAT3 proteins and decreases the expression of CCND1 and CCNA2 in pancreatic cancer cells." (PMID 37958903, 2023). "IL-6 activated the JAK2/STAT3 pathway, which accelerated cell cycle progression by promoting CyclinD1 expression in pancreatic cancer." (PMID 34165442, 2021). "It was documented that the expression of JAK2 and STAT3 was particularly high in pancreatic cancer tissues compared with para-cancerous tissues and it was intensely associated with a poor prognosis in pancreatic cancer patients." (PMID 34623971, 2021). "For example, IL-32α can inhibit JAK2 / STAT3 signaling pathway to inhibit IL-6-induced EMT and tumor cell invasion and metastasis in pancreatic cancer cells." (PMID 33097029, 2020). "Other researchers have reported that IL-32α can inhibit the JAK2/STAT3 signaling pathway and reverse the IL-6-induced EMT process in pancreatic cancer cells." (PMID 33097029, 2020). "As an effective inhibitor for Jak2/STAT3 pathway, AG490 reversed pancreatic cancer cell-induced inhibition of DC differentiation." (PMID 27556503, 2016). "Leptin signaling via JAK2/STAT3 enhances cell invasion and promotes the metastasis of human pancreatic cancer." (PMID 27036040, 2016). "We then tested the effect of the JAK2 inhibitor AG490 on the leptin-induced enhancement of the migration and invasion of the pancreatic cancer cells." (PMID 25948792, 2015). "Additionally, through JAK2/STAT3 downregulation, CuB reduced the size of pancreatic cancer xenografts in athymic nude mice compared to controls without apparent drug toxicities." (PMID 38397437, 2024). "Furthermore, numerous studies have demonstrated the unusually high activation of the IL-6/JAK2/STAT3 signaling pathway in a range of malignancies, including gastric, breast, liver, colorectal (CRC), colon, ovarian (OC), lung, and pancreatic cancers." (PMID 38666938, 2024). "In addition, one study reported that ginseng diol induced apoptosis in the pancreatic cancer cell lines PANC-1 and Patu8988 through the JAK2/STAT3 signaling pathway, limiting the progression of pancreatic cancer." (PMID 36313365, 2022). "It is reported that the inhibition of JAK2/STAT3 phosphorylation enhanced the apoptosis mechanism in PDACs, suggesting that it may be a critical action point in pancreatic cancer." (PMID 36500220, 2022). "LncRNA H19 is significantly upregulated in pancreatic cancer cell lines and facilitates pancreatic cancer metastasis and EMT by directly targeting miR-675-3p, which binds to SOCS5, a member of the SOCS protein family that negatively regulates JAK2/STAT3 signaling." (PMID 35819532, 2022).
pancreatic cancer (continued). "Notably, both SHC1-engaged SRC and gp130-activated JAK2 signals increased the phosphorylation of STAT3 [Y705], a critical step in pancreatic cancer progression." (PMID 34921158, 2021). "This indicates that the inhibition of pancreatic cancer cells by betulinic acid is through the targeting of mTOR signaling, rather than Nrf2 or JAK2." (PMID 32513155, 2020). "We also determined that betulinic acid inhibited pancreatic cancer by specifically targeting mTOR signaling rather than Nrf2 or JAK2." (PMID 32513155, 2020). "A dual inhibitor of STAT3 pathways induces death of tumor cells, indicating that suppression of the JAK2/STAT3 pathway may be a promising approach for the prevention and treatment of pancreatic cancer." (PMID 33029256, 2020). "Other groups reported that the IL-6/JAK2 signaling pathway inhibits autophagy, via p-STAT3, which activates Bcl-2 to regulate the expression of Beclin 1 and VPS34, while in pancreatic cancer, IL-6 induces mitochondrial localization of p-STAT3 at Ser727, upregulating autophagy flux." (PMID 32565533, 2019). "Neither trial of JAK2 inhibitor, however, attempted the concurrent targeting of the pancreatic tumor stroma and cancer cells." (PMID 30899415, 2019). "Finally, our data suggests that Cav-1 depletion in pancreatic cancer cells affects various pathways, particularly the JAK/STAT pathway, by decreasing activation of JAK2 and STAT3 and by increasing SOCS2, PIAS3, and DUSP5 inhibitory signals." (PMID 26065715, 2015). "Based on the role of MCPIP1 as a positive regulator inhibiting the IL6/JAK2/STAT3 axis, we propose that its expression may help identify patient subgroups with high IL6/JAK2/STAT3 axis activity (i.e., pancreatic cancer patients with strong metastatic potential)." (PMID 40874680, 2025). "As a result of our experiments, MBZ blocked S1P-induced phosphorylation of JAK2 and STAT3 pathways in pancreatic cancer cells, suggesting that this action may have an anticancer mechanism by regulating the expression of genes involved in the apoptosis of cancer cells." (PMID 36500220, 2022). "Furthermore, we explored the potential mechanism by which betulinic acid inhibited pancreatic cancer, and found that betulinic acid induces apoptosis by specifically through targeting mTOR signaling rather than Nrf2 or JAK2." (PMID 32513155, 2020). "This illustrates that the dampening of pancreatic cancer cells by fisetin targets AKT signaling, rather than JAK2." (PMID 34821587, 2021). "Besides, we determined the possible mechanism of repression by fisetin in pancreatic cancer and discovered that fisetin triggers apoptosis by specifically via targeting PI3K/AKT/mTOR cascade rather than JAK2 signaling." (PMID 34821587, 2021). "Furthermore, we established that fisetin repressed pancreatic cancer via explicitly targeting PI3K/AKT/mTOR signaling cascade and not the JAK2 cascade." (PMID 34821587, 2021).